BLOC1S2 (biogenesis of lysosomal organelles complex 1 subunit 2)
Description:
Component of the BLOC-1 complex, a complex that is required for normal biogenesis of lysosome-related organelles (LRO), such as platelet dense granules and melanosomes. In concert with the AP-3 complex, the BLOC-1 complex is required to target membrane protein cargos into vesicles assembled at cell bodies for delivery into neurites and nerve terminals. The BLOC-1 complex, in association with SNARE proteins, is also proposed to be involved in neurite extension (By similarity). As part of the BORC complex may play a role in lysosomes movement and localization at the cell periphery. Associated with the cytosolic face of lysosomes, the BORC complex may recruit ARL8B and couple lysosomes to microtubule plus-end-directed kinesin motor. May play a role in cell proliferation.
Synonyms: BLOS2; CEAP; MGC10120; FLJ30135; BORCS2; CEAP11
Tractability: PROTAC: ubiquitination databases record sites on it; its protein half-life has been measured.
Gene: Protein-coding gene on chromosome 10 (100,273,280 to 100,286,697, reverse strand). Ensembl gene ENSG00000196072.
Subcellular location: Cytoplasm, cytoskeleton, microtubule organizing center, centrosome; Lysosome membrane
Gene Ontology:
Molecular function: gamma-tubulin binding; protein binding
Biological process: extrinsic apoptotic signaling pathway via death domain receptors; lysosome localization; mitochondrial outer membrane permeabilization; anterograde axonal transport; anterograde synaptic vesicle transport; endosomal transport; melanosome organization; neuron projection development; organelle transport along microtubule; platelet dense granule organization; regulation of endosome size; regulation of lysosome size; cerebral cortex development; cerebral cortex neuron differentiation; embryonic brain development; embryonic hemopoiesis; hematopoietic progenitor cell differentiation; intracellular protein transport; neural precursor cell proliferation; Notch signaling pathway; protein catabolic process
Cellular component: BLOC-1 complex; BORC complex; gamma-tubulin complex; mitochondrion; cytoplasmic side of lysosomal membrane; axon cytoplasm; centrosome; cytosol; lysosomal membrane; lysosome
Genetic constraint (gnomAD): Loss-of-function variants: 12 observed, 17.92 expected, observed/expected ratio (o/e) 0.67, 90% interval 0.43 to 1.09. The upper end of that interval is the gene's LOEUF score, 1.09, which puts it in group 4 of 6, group 1 being the genes least tolerant of losing a copy. Missense variants: 140 observed, 175.76 expected, observed/expected ratio (o/e) 0.8, 90% interval 0.69 to 0.92. Synonymous variants: 66 observed, 67.88 expected, observed/expected ratio (o/e) 0.97, 90% interval 0.8 to 1.19.
Homologues: Orthologues: chimpanzee BLOC1S2 (99% identical), guinea pig BLOC1S2 (97% identical), rabbit BLOC1S2 (96% identical), rat Bloc1s2 (96% identical), pig BLOC1S2 (94% identical), mouse Bloc1s2 (93% identical), macaque BLOC1S2 (92% identical), dog BLOC1S2 (89% identical), tropical clawed frog bloc1s2 (78% identical), zebrafish bloc1s2 (76% identical), Drosophila melanogaster Blos2 (39% identical), Caenorhabditis elegans blos-2 (29% identical). Paralogues in human: RETSAT (20% identical), PYROXD2 (13% identical).
Diseases named in the same sentence as BLOC1S2 in open-access papers:
BLOC1S2 is named in the same sentence as 23 diseases in open-access papers, as found by Europe PMC text mining. Sharing a sentence is not in itself a finding about the gene and the disease. The quoted sentences say what the papers report.
breast carcinoma (1 paper, 2020). "High expression of both the ARL8B and BLOC1S2 genes, the latter of which is a BORC-subunit, was associated with poor survival rates in breast cancer patients and increased lymph node metastasis, both of which could account for the increased invasiveness." (PMID 33110168, 2020).
lung squamous cell carcinoma (1 paper, 2024). "For lung squamous cell carcinoma, 9 genes were causally related, comprising U91328.19, FLOT1, LINC00243, HLA-DQA1, HLA-DQB1, HLA-DQB1-AS1, HLA-DQB2, ZNF483 and BLOC1S2." (PMID 38834983, 2024).
lymph node metastasis (1 paper, 2020). "The ARL8B/BLOC1S2-high group was also found to be associated with an increased rate of lymph node metastasis." (PMID 33110168, 2020).
BLOC1S2 also shares sentences with these, for which no sentence is quoted: Telangiectasia (3 papers); cancer (2); Obesity (2); anorexia nervosa (1); anxiety disorder (1); autism spectrum disorder (1); depression (1); Hermansky-Pudlak syndrome (1); infection (1); leukemia (1); microcephalic osteodysplastic primordial dwarfism type II (1); ovarian carcinoma (1); pancreatic cancer (1); polycystic kidneys (1); psychiatric disorder (1); salivary gland tumors (1); schizophrenia (1); tumor (1); Varicose veins (1); venous ulceration (1).